CRP (C-reactive protein)
Diseases named in the same sentence as CRP in open-access papers (continued):
Sharing a sentence is not in itself a finding about the gene and the disease.
Stroke (continued). "In this study, patients had chronic underlying diseases, including stroke, cancer, and Parkinson’s disease, and CRP was a significant factor predicting early mortality, as seen in previous studies." (PMID 29954339, 2018). "Combined evidence suggests that the high-risk stroke population with CRP levels in the highest quartile are 2 to 7-fold more likely to develop stroke than those with CRP levels in the lowest quartile." (PMID 29245986, 2017). "Variation in the observed associations between CRP levels and the risk of incident stroke has been attributed to differences in patient demographics, the prevalence of comorbid conditions, genetics, and other environmental factors." (PMID 29245986, 2017). "For example, a recent study indicated that CRP levels can predict the risk of recurrent strokes among lacunar stroke patients." (PMID 27757207, 2016). "Kliper and colleagues reported that higher levels of C-reactive protein were associated with worse performance in cognitive tests after stroke." (PMID 26731740, 2016). "The aims of this study were 1) to identify clinical signs and symptoms for early diagnosis of post-stroke pneumonia, 2) to assess the usefulness of CRP as a marker of post-stroke pneumonia and 3) to identify an optimal diagnostic cut-off for CRP." (PMID 26937636, 2016). "The aims of this study were to describe early clinical features and to examine C-reactive protein (CRP) as a diagnostic marker of post-stroke pneumonia." (PMID 26937636, 2016). "CRP is an acute phase reactant and a marker of inflammation in the serum, as well as the risk of stroke." (PMID 27355961, 2016). "A recent systematic review of diagnostic approaches to pneumonia complicating stroke in research studies showed that CRP was rarely used in the diagnosis of post-stroke pneumonia, whereas WBC was incorporated more frequently as a diagnostic criterion." (PMID 26937636, 2016). "As a result, hs-CRP can be regarded as a high sensitive index in deciding the risk and prognosis of stroke." (PMID 27648042, 2016). "Results from a population-based cohort in prediction of a 90-day subacute recurrent stroke revealed a weak significant association for C-reactive protein." (PMID 27757207, 2016). "After application of exclusion criteria and additional exclusion of patients with suspected active infection (CRP ≥ 10 mg/dL) or rare stroke causes, the final study cohort included 644 patients." (PMID 27096104, 2016). "In fact, other studies reported that the association of CRP with clinical outcomes (3-month mortality, new vascular events, or stroke recurrence or death within 90 days) disappeared after adjusting for confounders." (PMID 27258004, 2016). "This cohort study was to investigate associations between C-reactive protein (CRP) and fatigue after stroke." (PMID 26599129, 2015). "Monomeric C-reactive protein (mCRP) appears in the ECM of ischaemic tissue after stroke, associating with microvasculature, neurons and AD-plaques, Aβ, also, being able to dissociate native-CRP into inflammatory, mCRP in vivo." (PMID 26335098, 2015). "CHF and stroke joint association models included CRP and glycohemoglobin; the angina joint association model included triglycerides and glycohemoglobin; and MI and CHD models included only glycohemoglobin." (PMID 25788869, 2015). "After multivariate adjustment, elevated hs-CRP concentrations (≥1 mg/L) showed persistent association with increased risk of all stroke and IS." (PMID 25191699, 2014). "The pathophysiological mechanism of the association between elevated CRP concentrations and the risk of stroke is yet fully elucidated." (PMID 25191699, 2014). "Cox proportional hazards regression was used to calculate the association between hs-CRP concentrations and all stroke, as well as its subtypes." (PMID 25191699, 2014).
Stroke (continued). "Stroke is associated with an increase of classic markers of the inflammatory response, such as C-reactive protein (CRP), erythrocyte sedimentation rate (ESR), total peripheral white blood cell (WBC) count, peripheral neutrophil count and body temperature." (PMID 24597828, 2014). "Several prospective epidemiological studies have demonstrated a consistent relationship between higher C-reactive protein (CRP) levels and an increased risk of cardiovascular events, including myocardial infarction, stroke, and cardiovascular death." (PMID 23737852, 2013). "After adjusting for age, sex, smoking status, alcohol use, education level, history of cardiovascular disease or stroke and CRP, the associations were still significant." (PMID 23725496, 2013). "Further, as shown here as well as in other studies, systemic CRP levels within the first week after stroke are associated with long–term outcome and correlate with brain infarct volume." (PMID 23977229, 2013). "We investigated association of plasma C3 and C3a levels to stroke, correlations to C-reactive protein (hsCRP), and associations with functional outcome at three months and two years post admission." (PMID 23977229, 2013). "C-reactive protein (CRP) is a biomarker of inflammation and a sensitive predictor of stroke, and high homocysteine (Hcy) is also associated with stroke." (PMID 24039853, 2013). "Most of the studies evaluating the probable association of CRP and stroke outcome have based their results only on a sole measurement of CRP." (PMID 24353532, 2013). "The baseline levels of inflammatory markers such as CRP and serum amyloid alpha independently predicted the risk of stroke, and atorvastatin reduced the levels of these biomarkers." (PMID 22364136, 2012). "Increased C-reactive protein (CRP) levels are associated with coronary heart disease, stroke, and mortality." (PMID 22524121, 2012). "Results of studies showed that the increased CRP levels were associated with functional impairment, coronary heart disease, stroke, and mortality." (PMID 22524121, 2012). "High CRP levels (42.1 mg/l) are associated with a higher incidence of acute thrombotic events including stroke and myocardial infarction." (PMID 22322513, 2012). "High levels of CRP, which is an acute-phase protein released by the liver in response to IL-6, are linked to worse outcome following stroke, and acute prestroke administration of human CRP is deleterious in experimental models." (PMID 22474516, 2012). "Several prospective epidemiological studies have demonstrated a consistent relationship between higher C-reactive protein (CRP) levels and increased risk of cardiovascular events, including myocardial infarction, stroke, and cardiovascular death." (PMID 22963582, 2012). "IL-6 stimulates liver CRP production, an acute phase reactant associated with risk of myocardial infarction (MI) and stroke." (PMID 20543948, 2010). "Our study showed that the long-term mortality was significantly associated with CRP even after adjusting for age, sex and stroke severity." (PMID 19400931, 2009). "There is some evidence that high levels in the blood of inflammatory markers (for example, interleukin-6 and C-reactive protein) are associated with poor outcomes after stroke—inflammation is the body's response to infection and to damage." (PMID 19901973, 2009). "A high admission CRP in ischemic stroke patients is clearly associated with more severe stroke and high long-term mortality." (PMID 19400931, 2009). "The positive association between high CRP and cardioembolic etiology is rather intricately related to stroke severity." (PMID 19400931, 2009). "Our study, in which CRP was measured within 24 hours after stroke onset, showed a crude association between high CRP and poor short-term functional outcome." (PMID 19400931, 2009). "Stroke severity was associated with admission CRP even after adjusting for age, sex, intravenous thrombolysis and the presence of DM." (PMID 19400931, 2009).
Stroke (continued). "There is a crude association between high CRP and short-term functional outcome which is likely secondary to stroke severity." (PMID 19400931, 2009). "C reactive protein is known to independently predict risk for myocardial infarction, stroke, peripheral artery disease and sudden cardiac death even among apparently healthy individuals." (PMID 19706169, 2009). "But as an inflammatory marker, it is also possible that high CRP is associated with underlying processes that cause a more severe stroke." (PMID 19400931, 2009). "Studies in patients who already had a stroke shows an association between high CRP and stroke presentation, outcomes and future vascular events." (PMID 19400931, 2009). "Our study in ischemic stroke patients shows that a high CRP at admission is associated with more severe stroke, cardioembolic etiology, poor functional outcome and high mortality." (PMID 19400931, 2009). "The likely etiology of stroke on the TOAST classification was statistically significantly associated with CRP (p = 0.04)." (PMID 19400931, 2009). "Admission CRP is associated with stroke severity and long-term mortality when measured at least 24 hours after onset." (PMID 19400931, 2009). "In this large cohort of stroke patients, we found that higher levels of IL-6, CRP, and white cell count were independently and significantly associated with poor outcome and death at 6 mo after stroke." (PMID 19901973, 2009). "High levels of CRP and clotting factors that was seen in the opium addicts in the present study, suggest that use of opium increase risk for heart attack or stroke." (PMID 18980684, 2008). "For instance, the inflammatory marker C-reactive protein (CRP) predicts incident stroke, coronary heart disease, and all-cause mortality." (PMID 17903293, 2007). "High-sensitive CRP (hs-CRP) was shown to be anindependent risk factor for MI, stroke, sudden death, andperipheral arterial disease in different prospectiveepidemiological studies and it can be decreased by statinsindependent of the LDL-level reductions." (PMID 17497040, 2007). "Although TNF‐α shows consistent associations with stroke risk, clinical translation currently favors measuring downstream inflammatory markers (e.g., hs‐CRP and IL‐6) for prediction; TNF‐α nevertheless strengthens multimarker signatures reflective of vascular inflammation." (PMID 41567175, 2026). "Similarly, multiple meta-analyses have demonstrated that elevated CRP, including high-sensitivity CRP, is strongly associated with mortality, recurrent stroke, and poor functional outcomes." (PMID 41464233, 2025). "The detection of C-reactive protein (CRP) could significantly predict a population with high risk of stroke." (PMID 40376266, 2025). "Although IL-6 and CRP are functionally linked, and the release of CRP depends on the IL-6 signaling in the liver, their associations with stroke parameters may differ." (PMID 41221512, 2025). "The reviewed literature further emphasises CRP’s potential as a predictive marker for stroke risk." (PMID 41296388, 2025). "We could therefore not assess the influence of these factors on the association between CRP and stroke outcomes." (PMID 40682467, 2025). "The causal impact of HOA on stroke persisted unaltered when adjusted for CRP levels in AS." (PMID 39787159, 2025). "Genetic predispositions may influence stroke risk, as polymorphisms in inflammatory markers (e.g., C-reactive protein, interleukin-6) have been associated with a threefold increase in postoperative stroke." (PMID 40278202, 2025). "Hs-CRP levels are not only associated with the overall prognosis of AF, but may also play a key role in the prognosis of stroke caused by AF." (PMID 40151456, 2025). "Overall, CRP and IL-6 levels and consequently the risk of a stroke incrementally increases from the NPD to PD to T2D group, as a result of worsening metabolic and inflammatory profiles, with prediabetes representing an intermediate stage of the inflammatory response." (PMID 41296388, 2025).
Stroke (continued). "A Mendelian randomization study highlighted a clear causal relationship between CRP and stroke." (PMID 40491586, 2025). "Notably, stroke patients with dysphagia demonstrating CRP levels >10 mg/L exhibit a 97% increased AP risk, primarily mediated through dysphagia-related infectious complications." (PMID 40529443, 2025). "CRP, along with its highly sensitive form (hs-CRP), is widely used to monitor the progression of atherosclerotic plaques, but also to assess cardiovascular risk, particularly for myocardial infarction or stroke." (PMID 40725061, 2025). "Regarding the positive association of CRP with cardiovascular disease, such as myocardial infarction and stroke, the lowering of its levels indicates a “pleiotropic”, anti-inflammatory effect of RET in this chronic systemic, low-grade inflammatory condition, with potential benefit in the future." (PMID 41154646, 2025). "Similarly, it has been demonstrated that elevated CRP levels prior to MT were significantly associated with worse outcomes and higher mortality in stroke patients." (PMID 40353608, 2025). "Is post-stroke statin use associated with changes in CRP levels in IS patients?" (PMID 41295435, 2025). "In addition, in atrial fibrillation patients, increased CRP levels were correlated to increased stroke risk, secondary vascular events, and mortality." (PMID 40949500, 2025). "CRP, an acute-phase reactant produced under IL-6 stimulation, is another well-established biomarker associated with stroke, with levels above 3.0 mg/L tripling stroke risk." (PMID 41362543, 2025). "Thus, like IL-6, elevated high-sensitivity CRP (hsCRP) has been associated with cognitive decline and recurrent stroke." (PMID 41542283, 2024). "Our study has important public health implications for the prevention of stroke events, suggesting that healthcare professionals need to consider patients’ METS-IR, urea, and CRP levels in order to adequately assess the risk of stroke and identify high-risk individuals in a timely manner." (PMID 39634177, 2024). "CRP has also been shown to play a role in mediating low-density lipoprotein uptake in macrophages, which is implicated in atherogenesis, and studies have also shown that CRP is an independent predictor of CHF risk after stroke or transient ischaemic attack (TIA)." (PMID 38233747, 2024). "The mediating effect of CRP explained only 3.64% of the relationship between sedentary behavior and stroke, which still suggests that sedentary behavior may affect stroke risk partly through inflammatory pathways." (PMID 39758197, 2024). "Meanwhile, our study also suggests that improving insulin sensitivity and regulating CRP and uric acid levels may be important for preventing the risk of stroke occurrence." (PMID 39634177, 2024). "Even after accounting for potential confounders in 6572 consecutive participants, higher baPWV and high-sensitivity CRP (hs-CRP) levels were linked to cardiovascular death, acute myocardial infarction, coronary revascularization, and stroke throughout a mean follow-up duration of 3.75 years." (PMID 38793018, 2024). "Inflammation plays an important role in the pathophysiology of stroke, and it has been suggested that inflammatory risk markers within neutrophils, lymphocytes and C-reactive protein may have a strong independent predictive value for stroke outcome." (PMID 39758197, 2024). "Elevated levels of CRP are associated with excess mortality in cardiovascular disease and stroke." (PMID 39916950, 2024). "In addition, lower HGS is associated with higher levels of inflammatory markers such as C-reactive protein, and inflammation is a known risk factor for stroke." (PMID 39406921, 2024). "Furthermore, the low-level inflammatory response detected by high-sensitivity CRP in patients with minor strokes was also a risk factor for stroke recurrence." (PMID 39777309, 2024). "After a stroke, CRP has also been shown to independently associate with poor functional outcome." (PMID 38732147, 2024).
Stroke (continued). "Inflammatory markers (IL-6 and CRP) are associated with post-stroke cognitive impairment." (PMID 38169754, 2024). "Mediation of the association between METS-IR and UA with Stroke in Charls by CRP." (PMID 39634177, 2024). "CRP, as an inflammation marker, is closely associated with stroke risk." (PMID 39450050, 2024). "Additionally, we measured the inflammatory protein C-reactive protein (CRP) that has been previously associated with poor outcome after stroke – and is indicative of stroke-induced systemic immune alterations." (PMID 39135051, 2024). "Recent Mendelian randomization study indicated that H. pylori is associated with the risk of stroke, in which CRP may mediate the association." (PMID 38678252, 2024). "In addition, the addition of inflammatory biomarkers (WBC or CRP) combined with eGFR to the basic model with conventional risk factors significantly improved risk prediction for post-stroke pneumonia and functional outcome." (PMID 39736651, 2024). "This highlights thesubstantial impact of smoking on systemic inflammation, as evidenced by elevated C-reactive protein levels.Elevated levels of C-reactive protein are associated with more severe stroke, higher Systolic blood pressure, and worse functional outcomes." (PMID 40092874, 2024). "Elevated CRP level may be an independent predictor of all-cause mortality, stroke, and major adverse cardiovascular events in patients with AF, and baseline CRP levels can provide important prognostic information for risk classification of patients in AF." (PMID 39030470, 2024). "Improving insulin sensitivity and regulating CRP and uric acid levels may be important for preventing the risk of stroke occurrence." (PMID 39634177, 2024). "Similarly, when we added CRP and eGFR to the basic model with conventional risk factors, the risk discrimination and prediction for post-stroke pneumonia and functional outcome was also significantly improved." (PMID 39736651, 2024). "The substantial variance in CRP levels among ischemic stroke patients across different studies might reflect the diversity in stroke severity and the presence of underlying conditions." (PMID 39258059, 2024). "In addition, linear risk relationships of CRP with coronary heart disease, stroke, and mortality in the healthy population have been found." (PMID 36936907, 2023). "The risk ratios for the association of per unit increase in hs-CRP levels with mortality, risk of recurrent stroke, and poor prognosis were as follows, respectively: 1.42 [95% CI (1.19–1.69); p < 0.001], 1.03 [95% CI (1.01–1.04); p = 0.003], and 1.27 [95% CI (1.10–1.47); p = 0.001]." (PMID 37342777, 2023). "A higher level of CRP in the acute phase of ischemic stroke may suggest an increased risk of CD after stroke." (PMID 37509012, 2023). "CRP is a positive acute-phase protein that has been associated with stroke prognosis." (PMID 37577267, 2023). "Whether the association of increased CRP with new cardiac complications represents a pathophysiological mechanism or a biomarker of high concomitant atherosclerotic burden among stroke patients is unclear." (PMID 37119383, 2023). "CRP may affect stroke risk via its effects on other markers of inflammation, particularly fibrinogen." (PMID 37808231, 2023). "In an individual participant meta-analysis of 160,309 people free of cardiovascular disease or stroke, log-transformed CRP concentration had a linear association with conventional cardiovascular risk factors, and a log-linear relationship with first ischaemic stroke." (PMID 41541100, 2023). "Furthermore, when SII was replaced with CRP, the highest tertile of CRP was also associated with the incidence of stroke (HR, 16.1; 95% CI, 1.97–132, P = 0.009) and MACCE (HR, 2.56; 95% CI, 1.19–5.53, P = 0.017) during the long-term follow-up." (PMID 37440549, 2023). "High C-reactive protein (CRP) levels are a risk factor for stroke." (PMID 36895041, 2023). "Only two studies explored the relationship between CRP and risk of stroke." (PMID 38071240, 2023).